GNA11 (G protein subunit alpha 11)
Diseases named in the same sentence as GNA11 in open-access papers (continued):
Sharing a sentence is not in itself a finding about the gene and the disease.
uveal melanoma (continued). "Two alterations were identified in GNAQ and GNA11, mutations that are usually associated with uveal melanomas and blue nevi." (PMID 28380455, 2017). "Mutations were found in 10 of the 19 uveal melanomas, with equal numbers of GNA11 and GNAQ mutations, but there were also two NRAS mutations." (PMID 28228113, 2017). "GNAQ and GNA11 lead mutations generate an upregulation of MET factor (related to the appearance of liver metastasis by uveal melanoma)." (PMID 28573105, 2017). "The heterotrimeric G protein α subunit oncogenes GNAQ or GNA11 carry Q209X or R183X activating mutations and are present with ~90% frequency in human uveal melanomas." (PMID 27348266, 2016). "Recently, two groups found that around 80% of uveal melanoma harbor GNAQ or GNA11 mutation and YAP/TAZ are constitutively stimulated in these specimens." (PMID 27412635, 2016). "Conversely, GNA11 mutations are 2.6 times more frequent than GNAQ mutations in uveal melanoma metastases." (PMID 27148356, 2016). "GNAQ and GNA11 are oncogenes when mutated in certain types of melanocytic lesions, being extremely frequent in uveal melanoma, which forms from melanocytes located in the eye." (PMID 27148356, 2016). "Isolated somatic GNA11 mutations have been found in uveal melanoma and single blue nevi (a lesion distinct from dermal melanocytosis both clinically and histologically)." (PMID 26778290, 2016). "As noted, tumours dependent on the Ras/Raf/MEK/ERK pathway include uveal melanomas harbouring oncogenic GNAQ/GNA11 mutations." (PMID 26059332, 2015). "Mutations in BRAF, KIT and NRAS are rarely seen in uveal melanoma; however more than 80 percent of uveal melanomas have mutations in GNAQ or GNA11." (PMID 26334521, 2015). "In pre-clinical tumour models, selumetinib demonstrates single agent anti-cancer activity, including in models of uveal melanoma harbouring GNAQ or GNA11 mutations." (PMID 26059332, 2015). "Activating mutations in GNAQ and GNA11, encoding members of the Gα(q) family of G protein α subunits, are driver oncogenes in uveal melanoma." (PMID 24743024, 2014). "Mutations of GNAQ and GNA11 can be found in Chinese patients as in Caucasian patients with uveal melanoma, with a higher frequency reported for Caucasian patients." (PMID 25280020, 2014). "These G-alpha protein mutations occur in the genes GNAQ and GNA11 and are seen at a high frequency in uveal melanomas, those melanomas that begin in the eye." (PMID 25030020, 2014). "The frequencies of GNAQ and GNA11 somatic mutations in uveal melanoma were 18% (9/50) and 20% (10/50), respectively." (PMID 25280020, 2014). "Mutations in the genes GNAQ and GNA11 are critical for development and progression of uveal melanoma and are associated with activation of the mitogen-activated protein kinase (MAPK) pathway." (PMID 25030020, 2014). "Based on these data, we propose a model in which GNAQ/GNA11 mutations, detected in the Gα subunit of heterotrimeric G proteins in the majority of primary uveal melanomas, are responsible for the activation of MAPK pathway under normoxic conditions." (PMID 25166211, 2014). "GNAQ or GNA11 mutations lead to an upregulating activation of the MAPKinase pathway and appear to be major contributors to the development of uveal melanomas." (PMID 25280020, 2014). "Our hospital-based study showed that mutation frequency of GNAQ and GNA11 in Chinese patients with uveal melanomas was 18% (9/50) for GNAQ and 20% (10/50) for GNA11 with an overall frequency of 38% (19/50)." (PMID 25280020, 2014). "Van Raamsdonk and her colleagues found somatic mutations in GNAQ or GNA11 in 83% of the globes with uveal melanomas." (PMID 25280020, 2014). "In conclusion, mutations of GNAQ and GNA11 can be found in Chinese patients as in Caucasian patients with uveal melanoma, with the reported frequency being higher in Caucasian patients." (PMID 25280020, 2014). "Mutations in GNAQ and GNA11 are mutually exclusive and are present in the vast majority of uveal melanomas." (PMID 24743024, 2014).
uveal melanoma (continued). "Activating mutations in exon 4 (R183) and exon 5 (Q209) of GNAQ and GNA11 are almost exclusively found in uveal melanoma, thus providing a highly specific marker for the presence of circulating tumor DNA (ctDNA)." (PMID 23634288, 2013). "Mutations in GNA11 at codon Q209 were found in 32% of primary uveal melanomas, 57% of the uveal melanoma metastases, and 7% of blue nevi." (PMID 23634288, 2013). "GNA11 was mutated in 7% of blue nevi and 32% of primary uveal melanomas and 57% of metastasis arising from uveal melanomas." (PMID 25562798, 2012). "Prompted by similar phenotypes in mice harboring germline mutations in GNAQ and GNA11, GNA11 was also evaluated in a series of uveal melanomas, blue nevi and other nevi." (PMID 25562798, 2012). "The five uveal melanoma cell lines had GNAQ or GNA11 mutations and were either moderately or highly sensitive to TAK733." (PMID 22515704, 2012). "The majority of uveal melanomas bear a mutually exclusive activating mutation in either GNAQ or GNA11, resulting in overlapping functions in melanoma cells with the constitutive upregulation of the MAPK pathway." (PMID 22515704, 2012). "GNAQ and GNA11 mutations at codon 209 were encountered in 21.7% and 56.5% of metastatic uveal melanoma samples, respectively." (PMID 21773036, 2011). "Most harbor GNAQ or GNA11 mutations, linking them genetically to uveal melanoma." (PMID 41183565, 2026). "For example, BRAF and NRAS mutations are prevalent in superficial spreading and nodular melanomas, NF1 loss is associated with chronic sun-damaged melanomas, KIT mutations are more common in acral and mucosal disease, and GNAQ/GNA11 mutations characterize uveal melanoma." (PMID 41283484, 2025). "In a previous study, we reported that ctDNA could be detected in patients with uveal melanoma via ultradeep sequencing of plasma-based GNAQ or GNA11 mutation." (PMID 41362626, 2025). "However, greater than 80% of uveal melanomas have activating mutations in GNAQ or GNA11, genes that encode for G protein alpha subunits." (PMID 38683104, 2024). "Overall, 83% of all investigated uveal melanomas had oncogenic mutations in either GNA11 or GNAQ." (PMID 39518110, 2024). "In addition, mutations in GNAQ and GNA11 occurred in the majority of uveal melanomas found in this study, which is consistent with the findings of previous research." (PMID 37649078, 2023). "The gene mutations of GNA11 were frequently observed in human uveal melanomas, implying that it could lead to the initiation of uveal melanomas." (PMID 36835134, 2023). "Finally, GNAQ/GNA11 mutations are characteristic of uveal melanomas and are only rarely present in cutaneous melanomas." (PMID 37373134, 2023). "Additionally, higher percentages of GNAQ and GNA11 mutations were observed in patients with uveal melanoma, and a higher percentage of SF3B1 mutations in patients with esophageal and uveal melanoma." (PMID 37649078, 2023). "GNAQ/GNA11 subtype: GNAQ/GNA11 mutations are found in 80–90% of uveal melanomas." (PMID 36676131, 2023). "Our analysis also shows frequent mutations of GNA11 in the TCGA UVM (uveal melanoma) cohort." (PMID 35975235, 2022). "Indeed, hot spot–activating mutations in GNAQ/GNA11, encoding Gαq proteins, are known to be driver oncogenes in uveal melanoma (UM), for which there are limited effective therapies currently available." (PMID 36596361, 2022). "Uveal melanoma (UM) with GNAQ/GNA11 mutations has been shown as YAP-dependent." (PMID 36347861, 2022). "GNA11 is considered to be an early driver mutation in leptomeningeal and uveal melanomas." (PMID 32373524, 2020). "However, only a few studies have reported somatic mutations in GNAQ or GNA11 in uveal melanoma in Chinese." (PMID 35693877, 2019). "Early activating mutations in GNAQ or GNA11 are present in about 80% of primary uveal melanomas." (PMID 31323802, 2019).
uveal melanoma (continued). "In light of the finding of these mutational hotspots in GNAQ and GNA11 in Caucasians, we hypothesized that somatic mutations in GNAQ or GNA11 may also be frequently observed in uveal melanoma in the Chinese population." (PMID 35693877, 2019). "Furthermore, greater than 80% of uveal melanomas possess oncogenic mutations in G-protein-α subunits associated genes GNAQ or GNA11 as found in our case." (PMID 29433557, 2018). "While a few GNAQ and GNA11 mutations were identified, they presumably represent functionally non-relevant bystander mutations, as none of the identified mutations were the activating R183 or Q209 mutations known to occur in uveal melanomas." (PMID 29559732, 2018). "Mutations in GNAQ and GNA11 account for up to 83% of all uveal melanoma, which suggests that inhibition of YAP/TAZ activity, either directly or by blocking pathways downstream of GPCRs, may be an effective treatment for this cancer." (PMID 29642615, 2018). "Mutations in the G-α-proteins GNAQ and GNA11 that occur in 91% of uveal melanoma also activate MAPK and PI3K/AKT pathways, which implies that the combination of MEK and AKT inhibitors may also be profitable for this patient group." (PMID 28938534, 2017). "Furthermore, GNAQ and GNA11 mutations blocking GTP hydrolysis were identified in melanocytic neoplasms such as uveal melanoma and blue nevi." (PMID 27034005, 2016). "GNA11 has a stronger association with metastatic uveal melanoma than GNAQ." (PMID 24743024, 2014). "Approximately, 80% of primary uveal melanomas have GNAQ or GNA11 mutations." (PMID 25030020, 2014). "Considering the genetic variations and their role in tumor genesis in different ethnic groups, we investigated the status of GNAQ and GNA11 mutations in uveal melanoma of Chinese patients to decrypt potential oncogenic differences between Caucasian and Chinese populations." (PMID 25280020, 2014). "In addition, constitutively active, oncogenic mutations in either GNAQ or GNA11 are found in ∼75% of common nevi of the dermis and in ∼83% of uveal melanomas." (PMID 23555837, 2013). "The GNAQ and GNA11 mutations associated with uveal melanoma and blue nevi occur almost exclusively in exon 5 (most commonly Q209L) and involve the glutamine residue within the ras-like domain, which plays an essential role in the GTP hydrolysis activity of this gene’s protein products." (PMID 23825798, 2013). "To examine whether oncogenic GNAQ or GNA11 mutations are required in uveal melanomas bearing NF1 mutations, we examined a uveal melanoma tumor from a patient with neurofibromatosis type 1, which is known to be caused by inherited heterozygous mutations in NF1." (PMID 23555837, 2013). "Preclinical data suggest that MEK inhibition with drugs like AZD6244 or GSK1120212 may be effective for uveal melanomas carrying GNAQ or GNA11 mutations." (PMID 22536370, 2012). "Also like GNAQ, although GNA11 is primarily viewed as relevant to uveal melanoma, anecdotal reports have found mutations in this gene in non-uveal melanoma patients." (PMID 21479172, 2011). "GNA11 mutations have been noted at 31.9% of uveal melanoma samples." (PMID 21773036, 2011). "INPP5A was recently identified as a drug target in uveal melanoma (UVM) with activating mutations in the guanosine nucleotide-binding protein Q gene (GNAQ) or its paralog guanosine nucleotide-binding protein alpha-11 gene (GNA11), which occur in approximately 90% of these cancers." (PMID 39995872, 2025). "Thus, GNAQ and GNA11 are essential biomarkers for uveal melanoma in diagnostic panels." (PMID 37576814, 2023). "The first mutation set encompasses the eight UM driver genes according to the TCGA study, divided into “uveal melanoma initiating mutations” (CYSLTR2, GNA11, GNAQ and PLCB4) and “second hit mutations with prognostic impact” (BAP1, EIF1AX, SF3B1 and SRSF2)." (PMID 39858540, 2025).
uveal melanoma (continued). "Most uveal melanoma cases are driven by activating mutations in GNAQ and GNA11 genes, which convey oncogenic signaling through the mitogen-activated protein kinase (MAPK) pathway." (PMID 41154654, 2025). "Opposed to skin melanomas, B-Raf Proto-Oncogene (BRAF) mutations are uncommon in uveal melanoma, while G Protein Subunit Alpha Q (GNAQ) and G Protein Subunit Alpha 11 (GNA11) gene mutations are very frequent." (PMID 40566630, 2025). "Uveal melanoma (UM), while exhibiting unique morphological features, shares considerable molecular disruptions with other conditions driven by GNAQ or GNA11 mutations." (PMID 39518110, 2024). "A key oncogenic event in uveal melanoma is the activation of YAP, resulting from mutations in GNAQ or GNA11, which encode α subunits of the Gq family of G proteins." (PMID 38182898, 2024). "Uveal melanoma (UM), recognized as the most prevalent primary intraocular malignancy in adults, is primarily driven by mutations in the GNAQ and GNA11 genes." (PMID 39518110, 2024). "In non-uveal melanomas, GNAQ/GNA11 mutations display a unique genetic profile characterized by a lower tumor mutational burden and fewer UV signature mutations than are common in cutaneous melanomas." (PMID 38474231, 2024). "This meta-analysis aimed to evaluate the prognostic significance of driver mutations, including GNAQ, GNA11, BAP1, and SF3B1, in the advancement of uveal melanoma." (PMID 39061150, 2024). "Initiating mutations in either Guanosine Nucleotide-binding Protein Q gene (GNAQ) or its paralogue, Guanosine Nucleotide-binding Protein Alpha-11 Gene (GNA11), act as a paramount driver in the oncogenic process and are present in 80–90% of uveal melanomas." (PMID 38732371, 2024). "The activation of YAP by GNAQ or GNA11 renders YAP a promising target for the treatment of uveal melanoma." (PMID 38182898, 2024). "The rarity and distinct behavior of GNAQ/GNA11 mutant non-uveal melanomas highlight the importance of ongoing research to develop effective treatments for this unique melanoma subgroup." (PMID 38474231, 2024). "The ERK family kinases are MAPK signaling components downstream of MEK1/2, and ERK activation in uveal melanoma has been observed in relation to GNAQ and GNA11 mutations." (PMID 38683104, 2024). "In studies of uveal melanoma, YAP has been seen to be activated in a manner independent from hippo in the GNA11 mutation variation of the disease, which suggests a more direct path from the mutated G protein signaling." (PMID 39598668, 2024). "In uveal melanoma, approximately 95% of the GNAQ or GNA11 mutations affect the p.Q209 site, while 5% affect p.R183." (PMID 38618955, 2024). "Mutations in the GNAQ/GNA11 gene activate the MAP kinase signaling pathway, a key factor in the development of uveal melanoma." (PMID 37628631, 2023). "Somatic mutations of GNA11/GNAQ, which excessively activate the MEK/ERK signaling pathway, are the most common cause of uveal melanoma with hotspot mutations mainly affecting Q209 and R183 residues." (PMID 37658401, 2023). "Rare mutations in CYSLTR2 and PLCB4, which function upstream and downstream of GNAQ/GNA11, respectively, have also been identified, demonstrating the importance of this pathway in uveal melanoma oncogenesis." (PMID 37966164, 2023). "Uveal melanoma (UM) is the most prevalent cancer of the eye in adults, driven by activating mutation of GNAQ/GNA11; however, there are limited therapies against UM and metastatic UM (mUM)." (PMID 37858338, 2023). "In a small subset of cutaneous melanomas, and in the vast majority of uveal melanomas, the activation of PAK1 is expected as a consequence of activating mutations in the GNAQ and GNA11 oncogenes, which reportedly signal through RAC1 and RAS." (PMID 37830586, 2023). "Additional mutations in EIF1AX and SF3B1 have been associated with a favourable prognosis subtype of uveal melanoma, whereas mutations in GNAQ/GNA11 are found in more than 90% of patients." (PMID 38201222, 2023).
uveal melanoma (continued). "Uveal melanoma is driven by oncogenic mutations in the heterotrimeric G protein subunit α (GNAQ) and in its paralog GNA11, which share > 90% peptide sequence identity and strikingly similar effects." (PMID 37966164, 2023). "Their effect has not been precisely studied, but their exclusivity with the GNAQ, GNA11, and CYSLTR2 mutations and PLCβ4 being downstream of these proteins suggest that PLCβ4 mutations have a similar effect on the oncogenicity of uveal melanomas." (PMID 35158973, 2022). "The structurally similar FR900359 and YM-254890 inhibit oncogenic GNAQ/GNA11 and promote potent cell cycle arrest and apoptosis in uveal melanoma." (PMID 35352024, 2022). "In contrast to cutaneous melanoma, mutations in BRAF are very rare in uveal melanoma, whereas mutations in GNAQ and GNA11 are common, and uveal melanoma has a much lower tumor mutational burden." (PMID 35021863, 2022). "PLCB4 mutations occur in approximately 5% of uveal melanoma and are mutually exclusive with GNAQ, GNA11, and CYSLTR2 mutations." (PMID 35158973, 2022). "This review aims to provide a current comprehensive view of what we know about GNAQ and GNA11 genes on oncogenesis, prognosis and therapeutic opportunities in uveal melanoma." (PMID 35804836, 2022). "Mutations in the GNAQ and GNA11 genes, which encode guanine nucleotide-binding protein G(q) subunit alpha and guanine nucleotide-binding protein subunit alpha-11, are detected in more than 80% of primary uveal melanomas." (PMID 35804893, 2022). "The potential role of wild-type CYSLTR2 in GNAQ, GNA11 or PLCB4 mutant uveal melanomas was studied in publicly available bulk and single cell sequencing data." (PMID 33588787, 2021). "Combined exposure of sotrastaurin with alpelisib, a selective PI3K-alpha inhibitor, resulted in synergistic cell death in GNAQ and GNA11 mutant uveal melanoma cell lines and tumor growth inhibition in a GNAQ-mutant xenograft tumor model." (PMID 34771668, 2021). "Typical uveal melanoma-related mutations were found in seven cases (15%): one case with GNAQ p.R183Q, one with GNA11 p.R183C, two with SF3B1 p.R625C/H, and three with BAP1 missense/nonsense supposedly somatic mutations." (PMID 34359736, 2021). "Uveal melanoma is the most common primary ocular malignancy in adults, characterized by gene mutations in G protein subunit alpha q (GNAQ) and G protein subunit alpha 11 (GNA11)." (PMID 34830903, 2021). "Uveal melanomas frequently show guanine nucleotide-binding protein G(q) GNAQ and GNA11 mutations, which enhance MEK-ERK1/2 signaling." (PMID 34073463, 2021). "Significant insight has been gained into the pathways that are altered in uveal melanoma, with mutually exclusive activating mutations in the GNAQ and GNA11 genes being found in over 90% of patients." (PMID 34944815, 2021). "We also detected nucleotide transitions resulting in gene activation in NRAS (Q61K, Q61R), in the promoter region of TERT (chr5:1295250 G > A), and in GNA11 (R183C), the latter being frequent in uveal melanoma and primary meningeal melanocytic tumors." (PMID 33578810, 2021). "Taken together, these findings indicate that mutations in GNAQ, GNA11 and CYSLTR2 – all recurrently found in uveal melanomas – can also present as an independent somatic event in benign uveal nevi." (PMID 33588787, 2021). "In uveal melanoma, GNAQ and GNA11 gene mutations are frequently found and prognosis is based on mutation status of BAP1, SF3B1 and EIF1AX genes." (PMID 33396957, 2020). "In uveal melanoma ATCG samples, only one among 80 uveal melanoma patients revealed a missense mutation in YAP (G369R) co-occurring with GNAQ R183Q and GNA11 R183C." (PMID 32850962, 2020). "In uveal melanoma, hot spot somatic mutations in GNAQ/GNA11 lead to amino acid substitutions in exon 5 (p.Q209L or p.Q209P) or in exon 4 (p.R183C)." (PMID 32532044, 2020).